VIM (vimentin)
Diseases named in the same sentence as VIM in open-access papers (continued):
Sharing a sentence is not in itself a finding about the gene and the disease.
tumor (continued). "Analysis using immunohistochemistry shows the presence of cytokeratins, S100 protein, GFAP, Vimentin, and SMA staining, indicating the tumor's mixed epithelial and stromal composition." (PMID 39221300, 2024). "Immunohistochemistry revealed that tumour cells were positive for cytokeratin (clones AE1/AE3), while stromal cells were positive for vimentin (clone V9)." (PMID 39340734, 2024). "Recent research has demonstrated a subset of aggressive CTCs that express vimentin on their surface and exhibit an EMT phenotype, increasing the likelihood of tumor recurrence." (PMID 38685125, 2024). "The tumors retained the characteristics of the original tumor, as confirmed through hematoxylin and eosin staining and histochemical analysis using markers such as AE1/3, desmin, S-100, CD34, and vimentin." (PMID 39737254, 2024). "A comparison of gene expression in normal ovaries and tumor tissue revealed decreased mRNA levels of ITGA5 and VIM in OC patients." (PMID 38786089, 2024). "In this study, tumor cells exhibited diffuse strong positivity in 98 cases (99%) for S100, 97 cases (98%) for SOX10, and 97 cases (98%) for Vimentin." (PMID 39158355, 2024). "Commonly used molecular markers include vimentin, S100 protein and CD99, which collectively assist in determining the cellular origin and genetic lineage of the tumor." (PMID 39483928, 2024). "The expressions of vimentin, α-SMA, and TGFβ1 have been reported as prognostic markers or therapeutic targets for different tumor types." (PMID 38791274, 2024). "Immunohistochemically, most tumour cells were strongly positive for keratin (AE1/AE3) and focally positive for EMA, with the typical squamous cells focally positive for 34betaE12 and Vimentin." (PMID 39816396, 2024). "Further analysis of the HCT116 tumour tissue lysates showed that BEST4 deterred EMT by upregulating E-cadherin, and downregulating VIM and TWIST1." (PMID 39699952, 2024). "The results revealed the downregulation of E-cadherin, coupled with the upregulation of vimentin and VEGFA in tumor tissues of patients exhibiting osimertinib resistance, compared with those in tissues from patients before receiving osimertinib." (PMID 39375945, 2024). "To evaluate whether melittin inhibits tumor cell invasion and metastasis by interfering with EMT progression, we examined the expression of EMT-associated proteins, including MMPs (MMP2, MMP9), E-cadherin, N-cadherin, Vimentin, and related regulatory protein, in both in vivo and in vitro models." (PMID 39519238, 2024). "GBM tissue samples were also shown to stain positively with markers for proliferation (Ki-67) and migration (vimentin), typical of the stem cell populations in GBM neoplasms that show strong potential for expansion and invasion." (PMID 38803685, 2024). "N-cadherin and vimentin are positively correlated with EMT and are considered its markers, whereas E-cadherin acts as a tumor suppressor protein." (PMID 39723390, 2024). "The examination indicated positive Vimentin findings in the cytoplasm and positive FLI-1 in the nuclei of the tumour cells." (PMID 38735214, 2024). "Intriguingly, the different TGF‐β concentrations determine the diverse transition of epithelial, p‐EMT, and mesenchymal states in tumor cells via influencing the expression of EMT‐TFs, E‐cadherin, and vimentin." (PMID 39092293, 2024). "At the molecular level, tumor tissues of the HFD group mice exhibited high expression of Ki-67 and vimentin, but low expression of BAX." (PMID 38319449, 2024). "Subsequently, we performed IHC staining analysis of VM-related markers, including VM markers VE-cadherin, Fibronectin 1 (FN1), SERPINE2, tumor microenvironment markers MMP2 and MMP9, epithelial cell marker E-cadherin and mesenchymal cell marker vimentin." (PMID 38164156, 2024).
tumor (continued). "The morphological heterogeneity is apparent since it can be observed that the morphology of tumor cells that undergo EMT switches from round to fusiform due to the change of their cytoskeleton and generation of vimentin filaments." (PMID 39092293, 2024). "Typical findings associated with stromal sarcoma involve positive expression of vimentin, cytokeratin, CK7, CD99, Bcl-2, SS18-SSX2, and SYT-SSX in the tumor cells." (PMID 39079400, 2024). "E-cadherin is an essential component of the cytoskeleton and intercellular adhesion, while vimentin is a specific protein expressed by mesenchymal cells, indicating the initiation of EMT and the heightened invasive state of tumor cells." (PMID 38294713, 2024). "The results demonstrated that tumor tissues from the RBE CTRL group exhibited lower E-cadherin expression and higher Vimentin expression compared with the RBE DCLK1-KO group." (PMID 38980538, 2024). "(ii) With apparent E-cadherin upregulation and vimentin downregulation, P-BS-CM1 → P-CM2 increased epithelial properties and decreased mesenchymal features of tumor cells, indicating EMT inhibition." (PMID 38553476, 2024). "Immunohistochemical results showed that the tumor cells positively expressed smooth muscle actin (SMA), anaplastic lymphoma kinase (ALK), CD117, vimentin, but negatively expressed cytokeratin (CK), Desmin and Dog-1." (PMID 39193013, 2024). "We subsequently tested the epithelial membrane antigen (EMA), vimentin, CD68, and CD163 in tumor tissues, all of which showed positive expression." (PMID 39432588, 2024). "The tumor was positive for muscle markers like Smooth Muscle Actin (SMA), vimentin, keratin and caldesmon." (PMID 38449999, 2024). "This combination not only reduces cell proliferation, but also hinders metastasis by downregulating key proteins, such as vimentin and MMP9, while affecting signaling pathways, such as Akt and STAT3, to enhance tumor inhibition." (PMID 39741633, 2024). "Histopathological examination of the resected tumor revealed typical features of RDD, including large histiocytes, lymphocyte infiltration, and immunohistochemical positivity for CD68, S-100, and Vimentin." (PMID 39678509, 2024). "Immunostaining of tumor tissue sections from lung biopsies showed weak positive signals for PIM1, p-GSK3β (Ser9), and Vimentin before treatment, which subsequently became strong positive signals upon development of acquired osimertinib resistance." (PMID 39227379, 2024). "At immunohistochemistry the neoplastic samples expressed both vimentin and EMA, in all the tumor area and from 70% to 90% of the entire tumor area, respectively." (PMID 39055601, 2024). "The decrease in the invasion and migration ability of tumor cells is often accompanied by increased expression of the core molecule CDH1, decreased expression of CDH2, and decreased expression of VIM." (PMID 38397980, 2024). "In agreement with this, we reported lower levels of vimentin by western blot after CHIR99021 treatment of T98G cells, highlighting the effect of GSK-3 inhibition in tumor migration." (PMID 38907776, 2024). "SSX expression affects EMT in tumor cells, and the downregulation of SSX expression can inhibit the promoting effect of vimentin and MMP2 proteins on tumor cell invasion." (PMID 38896069, 2024). "Vimentin, as an essential cytoskeletal protein, plays a crucial role in epithelial-mesenchymal transition (EMT), a process in which tumor cells acquire migratory and invasive properties, leading to metastasis and chemoresistance." (PMID 39090304, 2024). "Herein, the tumor showed positive expression for CD31, vimentin, and CD10, which led to the final diagnosis of EAS." (PMID 39687884, 2024). "Consistently, TS3 tumor has higher expression of epithelial CDH1 (coding for E-cadherin) and lower expression of Vimentin compared to the EMT cluster, suggesting TS3 tumor state is largely epithelial in nature despite upregulation of some genes shared in EMT." (PMID 39289380, 2024).
tumor (continued). "The upregulated cysteine‐rich 61 (CYR61), a secreted protein involved in tumor metastasis, is reported to induce expression of EMT‐TF Twist, vimentin, and N‐cadherin." (PMID 39092293, 2024). "Of note, staining for E-CAD, VIM, GLUT1, pAMPK revealed co-expression of these markers in control JIMT-1 tumours, indicative of hybrid metabolism in E/M cells." (PMID 38238426, 2024). "The relevance of prognostic biochemical, histological, and imaging parameters, such as IGF-2 levels, vimentin, CD34, bcl-2, or CD99 positivity but cytokeratin negativity, and tumor size > 10 cm, is unclear." (PMID 39138498, 2024). "The tumours are positive for AMACR, CK7, Vimentin, and CD10 and need to be differentiated from papillary neoplasm with reverse polarity which are GATA3 positive, vimentin negative, and AMACR positive." (PMID 38265103, 2024). "Of note, tumor cells in 12 cases (80%) with SMARCA4‐UTs expressed vimentin, whereas only 5 cases (41.7%) with SMARCA4‐NSCLCs were positive for vimentin." (PMID 38124509, 2023). "Immunohistochemically, the tumor cells showed diffuse positivity for TFE3, CD10, vimentin, and IFITM1." (PMID 36707859, 2023). "On the one hand, the tumor hybrids expressed “classical” M-genes, such as CDH2 and VIM, suggesting that they are rather in a M state." (PMID 38139138, 2023). "E-cadherin, N-cadherin, and Vimentin are critical epithelial–mesenchymal transformation (EMT)-related proteins, which that modulate cell migration and tumor invasiveness." (PMID 36755950, 2023). "Seven hub genes (AXL, EFEMP2, VIM, EHD2, FSTL3, ALOX5, HSPB8) were downregulated in tumor samples, while COL3A1 was upregulated in tumor samples in the TCGA dataset." (PMID 37291533, 2023). "The type III intermediate filament vimentin is a signature of EMT and is frequently up-regulated during tumor progression." (PMID 37976356, 2023). "The expression of DPY30, N-Cadherin, and Vimentin were upregulated in the CRC tumor region (bottom right), but the expression level of E-Cadherin in the CRC tumor region (bottom right) was lower than that in para-tissues (upper left)." (PMID 38115111, 2023). "Vimentin, a pivotal component of the cytoskeletal protein, is remodeled and upregulated during EMT, resulting in tumor cell survival and migration." (PMID 37260179, 2023). "The upregulation of MMP-2, MMP-9 and Vimentin and the inhibition of E-cadherin in tumor cells will promote EMT and contribute to tumor invasion." (PMID 37367063, 2023). "In pediatric GBM, according to WHO grade IV of this tumor, few GFAP fragments were detected, and vimentin fragments, when present, showed a different distribution between male and female patients, highlighting sexual dimorphism in pediatric GBM disease." (PMID 37761239, 2023). "This inhibitory effect of TEPA on TGF-β is also evidenced by a significant decrease in VIM, MMP-9 and MMP-14, which play a key role in promoting tumor invasion." (PMID 37480151, 2023). "The correlation between MVI occurrence and primary disease, age, gender, tumor size, tumor stage, and immunohistochemical characteristics of 13 proteins, including GPC3, CK19 and vimentin, were statistically analyzed." (PMID 36973651, 2023). "Previous studies have shown that enhanced expression of mesenchymal markers, like N-cad and VIM, are important proteins in initiating EMT in tumours like the bladder, breast, colon, and prostate." (PMID 37174052, 2023). "In subsequent studies, we also found that the exosomes of M2 macrophages enhanced the migration ability of tumor cells and promoted the TMT process by regulating the expression of MMP-2, MMP-9, Vimentin, and E-cadherin." (PMID 37367063, 2023). "The EWS tumor cells usually express CD99, vimentin, synaptophysin (Syn), and neuron-specific enolase (NSE) but do not express common antigen (LCA), CD20, and chromaffin granin (CgA)." (PMID 37469664, 2023). "The upregulation of N-cadherin, Vimentin and MMP2 facilitates the process of EMT and contributes to the metastasis of tumor cells." (PMID 37904179, 2023).
tumor (continued). "The PI3K/Akt pathway targets GSK3β/β–catenin to regulate ZEB1 transcription and subsequently regulates the expression of cytokeratins, vimentin, and MMP2 for tumor cell adhesion, invasion, and migration." (PMID 37627900, 2023). "EMT promotes tumor metastasis by upregulating or downregulating the expression of epithelial markers such as MMP-2, MMP-9, VEGF, vimentin, E-cad, and N-cad." (PMID 37020791, 2023). "Vimentin, as a typical marker for EMT, is overexpressed in various epithelial cancers and correlates well with accelerated tumor growth, invasion, and poor prognosis." (PMID 36755950, 2023). "Looking further downstream, MACC1 was frequently found to induce a mesenchymal phenotype in multiple tumor types, through the measurement of EMT markers, such as increased expression of vimentin and N-cadherin and reduced expression of E-cadherin." (PMID 37051546, 2023). "The results of transcriptome sequencing after knockdown of SNHG25 in HCT-116 cells showed that the expression of several tumor metastasis-related genes changed significantly (MMP2, VIM and CDH1), among which the expression of MMP2 decreased most." (PMID 37751586, 2023). "In combination with EpCAM, we stained tumour specimens for CD24 as a second marker of plastic EMT CSCs, and Vimentin as a mesenchymal marker to identify cells that have undergone EMT." (PMID 37975646, 2023). "Furthermore, while invading myoepithelial cells were Vimentin positive, luminal cells maintained expression of the epithelial specific marker EpCAM, demonstrating collective invasion and maintenance of the epithelial phenotype observed in tumour invasion 33–36." (PMID 36864079, 2023). "To validate the in vivo effect of the anti-TGF-β moiety of Y332D, we investigated the EMT-related markers E-cadherin, Vimentin, N-cadherin and the CAF marker α-SMA by IF staining assay in H22 tumor model." (PMID 37573354, 2023). "Results showed that the protein levels of N-cadherin, Vimentin, Slug, p-HER2, p-EGFR, p-ERK1/2, MMP9 and MMP14 increased significantly in PLC/PRF-5LL−37 xenograft tumor; while significantly decreased in PLC/PRF-5LL−37 xenograft receiving si-LL-37 treatment." (PMID 36656313, 2023). "There was a significant correlation between the mRNA expression of the EMT (epithelial–mesenchymal transition) markers CDH1 (E-cadherin) and VIM (vimentin) and high CYSLTR1 gene expression in tumor samples." (PMID 36834820, 2023). "In this study, we observed that tumor growth inhibition is directly related to α-SMA and VIM expression." (PMID 37901237, 2023). "It is well-known that E-cadherin, N-cadherin, and Vimentin are critical EMT-related proteins, which play pivotal roles in modulation of cell migration and tumor invasiveness." (PMID 36755950, 2023). "These ingredients can potentially decrease the levels of inflammatory cytokines (such as IL-6 and TNF-α), inhibit the expression of tumor-related factors (such as JAK2/STAT3, MMP-9, and vimentin), and increase immune cell activity." (PMID 37742025, 2023). "The transcription factor facilitates EMT, tumor angiogenesis and chemoresistance by upregulating the expression of key intermediaries such as VEGF, vimentin, HIF-1α and P-glycoprotein." (PMID 37924112, 2023). "Immunohistochemically, tumor cells were positive for CK, EMA, Vimentin, CD117, CK7, Mammaglobin, S100 and SOX10, but negative for DOG1, CD56, Cga, Syn, CK20, Calponin, SMA, NapsinA and TTF1." (PMID 37803309, 2023). "We investigated the relationship between E-cadherin, vimentin, and HMGA expression and found a statistically significant relationship in PDAC, AAC, and all neoplasia groups." (PMID 37787719, 2023). "IHC staining of both cell lines and the primary tumor tissue confirmed a stable expression of CCA tumor markers CK7, CK19, and e-cadherin, and the positive staining of stromal cells for vimentin and CAF markers α-SMA, TNC, and PDGFRB." (PMID 36980644, 2023).
tumor (continued). "Hematoxylin and eosin (HE) staining of tumor tissue specimens, along with immunohistochemistry (IHC), were conducted to evaluate the expression levels of Ki67, GRP78, N-cadherin, Vimentin, and ABCG2." (PMID 37934581, 2023). "We show that an invasive phenotype of the tumor, stimulated by enteric ETBF infection, is further supported by decreased E-cadherin and increased N-cadherin and vimentin expression, as well as nuclear accumulation of β-catenin and cleaved Notch1." (PMID 37503343, 2023). "We have shown that immunofluorescent antibody co-staining for EpCAM, Vimentin and CD24 can separate disseminating EMT CSCs from the stromal content of human tumours, a challenge which has confounded previous attempts to develop a predictive EMT signature." (PMID 37975646, 2023). "E-cadherin, Vimentin, N-cadherin, Fibronectin, Snail, Slug, Twist, and ZEB1 are crucial biomarkers and regulators of EMT, an important initial step of tumor metastasis." (PMID 37283789, 2023). "We investigated how SMPDL3B affects various key EMT proteins (E-cadherin, ZO-1, vimentin, and MMP-9) because epithelial-mesenchymal transformation (EMT) is a significant route of tumor cell migration and invasion." (PMID 38813495, 2023). "By combining EpCAM as a tumour lineage and EMT CSC marker, Vimentin as a mesenchymal marker, and CD24 as a plastic EMT CSC marker, we aimed to identify tumour cells that have undergone EMT and disseminated into the surrounding stromal region." (PMID 37975646, 2023). "Expression of EpCAM, Vimentin and CD24 was then analysed for every nucleated cell in every imaging field that included both tumour and stroma (3500 manually curated imaging fields across the 24 tumours)." (PMID 37975646, 2023). "Further evidence of aggressive tumor growth of the WSHFD-EL4 mice was showed by Western blot analysis of the protein levels of cyclin D1, c-Myc, and E-cadherin and Vimentin for epithelial–mesenchymal transition (EMT) in comparison with the CD-EL4 mice." (PMID 36600310, 2023). "E‐cadherin, N‐cadherin and Vimentin are essential proteins involved in EMT, while MMP‐9 is a critical protein in tumour proliferation." (PMID 37859585, 2023). "The notable immunohistochemical characteristics of these tumours are SMA expression and partial expression of desmin, vimentin and ALK." (PMID 36855132, 2023). "To this end, we assessed by Western blot the protein expression of several markers known to regulate tumour proliferation and invasion, such as Cyclin D3, CDK 2/4/6, TCF 1/7, Integrin beta-1, MT1-MMP, SNAIL, Vimentin, ZEB1, and ZO-1." (PMID 37887342, 2023). "Analysing this dataset for EpCAM, Vimentin and CD24 co-expression, we found that 12% of tumour cells (267/2215) were EpCAM+Vim+CD24+." (PMID 37975646, 2023). "The mRNA levels of CCR2, CCL2, VEGF, NF-κB, c-Myc, vimentin, and IL33 were determined in the CT26 cell line and then tumor tissues (after 21 days), by qRT-PCR." (PMID 37325423, 2023). "Immunohistochemically, tumor cells were positive for CK, EMA, Vimentin, CD117, CK7, S100, Mammaglobin and SOX10." (PMID 37803309, 2023). "The immunohistochemical examination is based on positivity for vimentin, desmin, CD34, hormone receptors (estrogens and progesterone, up to 80% of cases), S100, and a low Ki67 (<1% tumor cells)." (PMID 37629707, 2023). "Compared to vimentin, NLRP11 and vimentin‐K104Ac showed better tumor specificity, reflecting the differences between EMT‐mediated tumor cells and mesenchymal cells." (PMID 37424170, 2023). "After 15 days of treatment, E-cadherin, CD68, and CD8 were increased, while vimentin, STAT3, NF-κB, CD163, and CD25 were reduced (as detailed in Table Expression, B and 8 A) in tumours of Balb/c mice when compared to the control group." (PMID 36857852, 2023). "These analyses also showed that expression of VIM, TGFβ1, α-SMA, CD44 and CD133 had significantly high expression in metastatic compared to primary tumours." (PMID 37174052, 2023).